RNU6-343P (RNA, U6 small nuclear 343, pseudogene)
Gene: Small nuclear RNA gene on chromosome 12 (56,588,518 to 56,588,621, forward strand). Ensembl gene ENSG00000201579.
Homologues: Orthologues: chimpanzee U6 (100% identical), macaque U6 (95% identical). Paralogues in human: RNU6-11P (93% identical), RNU6-37P (93% identical), RNU6-12P (92% identical), RNU6-13P (92% identical), RNU6-25P (92% identical), RNU6-32P (92% identical), RNU6-41P (92% identical), RNU6-812P (92% identical), RNU6-1 (91% identical), RNU6-17P (91% identical), RNU6-18P (91% identical), RNU6-2 (91% identical), and 1290 more.